LGALS3BP (galectin 3 binding protein)
Diseases named in the same sentence as LGALS3BP in open-access papers (continued):
Sharing a sentence is not in itself a finding about the gene and the disease.
tumor (continued). "In concordance with our observations at the proteome and transcriptome level, LGALS3BP positive staining was numerically increased in recurrent HCC tumor explants, compared to non-recurrent, when examining the 11 samples from our discovery cohort." (PMID 34794390, 2021). "Human LGALS3BP has been purified from culture medium of tumor cell lines, serum and milk and shown to be a large non-covalent oligomeric protein with a molecular mass of ~ 1000 kDa." (PMID 34565385, 2021). "The prognostic role of LGALS3BP was also evaluated by immunohistochemistry in tumor tissues of a consecutive series of node-negative breast cancer patients." (PMID 34565385, 2021). "Additionally, four proteins (Triosephosphate isomerase, TPI1; Galectin-3, LGALS3; Galectin-3-binding protein, LGALS3BP; Filamin-A, FLNA) showed average immunostaining in normal tissue and high in tumor tissue." (PMID 32197468, 2020). "In the present study, we confirm and extend these findings by showing that LGALS3BP knock-down human CRC cells formed large tumors when implanted in nude mice and that intra-tumor delivery of human recombinant LGALS3BP induced regression of established CRC xenografts." (PMID 26219351, 2015). "Moreover, we identified novel substrates like LGALS3BP, ITGB8, CD36, and ECE1, which may contribute to malignant tumor progression." (PMID 39937175, 2025). "Normal and tumour tissues from such patients were analysed by qRT-PCR for the following 12 genes; six from RNA-seq: CLDN1, MAGEB2, CD24, CEACAM6, IL1B and ISG15 and six from RNA-seq and proteomics cross-linking: AKR1C3, TNFAIP2, RAB7A, LGALS3BP, PSCA and SSRP1." (PMID 36428603, 2022). "Therefore, they revealed that both overexpression of miR-596 and knockdown of LGALS3BP suppressed cell proliferation and induced apoptosis in OSCC cell lines, suggesting that LGALS3BP might act as an oncogene in this type of tumour." (PMID 34565385, 2021). "Similarly, immunohistochemical analysis revealed that SKNAS, but not hNB tumor xenografts, were positive to LGALS3BP." (PMID 33076448, 2020). "The lack of correspondence between exosomes and tumor tissues for VASP, LGALS3BP, MYH9 and LTBP1 could be due to the fact that these vesicles are loaded through active mechanisms." (PMID 37947594, 2023).
infection (31 papers, 2010 to 2026). The state of being infected such as from the introduction of a foreign agent such as serum, vaccine, antigenic substance or organism. "Previously generated Lgals3bp−/− animals were noted for increased susceptibility to infections, however, an attenuated WNV strain was used in our study, which can potentially explain the lack of increased lethality or higher viral titers." (PMID 39062523, 2024). "Marc-145 cells were transfected with either empty vector (EV) or LGALS3BP plasmids for 24 h, followed by infection with 0.1 multiplicity of infection (MOI) PRRSV HuN4 for an additional 24 h." (PMID 41090922, 2025). "To determine whether Lgals3bp impacts acute infection with WNV, we generated Lgals3bp−/− on the C57BL6/J background by targeting exon 2 of the Lgals3bp gene using CRISPR-Cas9 to induce a frameshifting mutation." (PMID 39062523, 2024). "For example, maintaining the appropriate TGF-β pathway activity, leukocyte migration ability, and LGALS3BP level might be helpful for eliminating clinical symptoms at the early stage of infection." (PMID 35958562, 2022). "Based on our previous RNA-seq results, LGALS3BP was significantly upregulated in response to both HuN4 and SD53 infections at 3 days post-infection (dpi), as shown in a heatmap." (PMID 41090922, 2025). "The 17 DEGs upregulated after infection with huH1N1 were shared with the swH1N1 infection (DDX58 (RIG-I), RSAD2 (Viperin), MX2, MX1, OAS1, ANGPTL4, IRF7, ISG15, IFIT1, ISG12(A), DDX60, BST2, IFI44, XAF1, LGALS3BP, RTP4, and IFI6)." (PMID 39247193, 2024). "Taken together, upregulation of neither LGALS3BP nor IFIT1 mRNA was detectable in Calu-3 cells after infection with SARS-CoV-2, in line with SARS-CoV-2’s ability to prevent efficient recognition by cell-intrinsic innate immunity." (PMID 37162650, 2023). "In addition, following a primary infection, the LGALS3 gene in the HSF flock and the LGALS3BP gene in the TSF flock were significantly induced in the abomasum of resistant sheep." (PMID 30678719, 2019).
bacterial infections (6 papers, 2021). "Galectin-3-binding protein (LG3BP), also known as Mac-2-binding protein, is a multifunctional protein involved in innate immunity and host response to viral and bacterial infections." (PMID 33785758, 2021). "Galectin-3-binding protein (LG3BP) is a glycoprotein with innate immune function in viral and bacterial infections." (PMID 34972134, 2021). "The rise in circulating LGALS3BP is not observed in non-COVID-19 sepsis ICU patients, highlighting the specificity for viral over bacterial infections." (PMID 34099652, 2021).
immune system diseases (1 paper, 2018). "DEGs that enriched to “immune system diseases” played critical roles in cell-matrix communication (THY1, LVRN, LUM, TIMP3, SPOCK1, LGALS3BP, FAT2, and SERPINE2) as well as inflammation (IL1R2, CD22, PTGES, TNFSF10, IL2RB, C3, SERPING1, and IL-17RE)." (PMID 30131724, 2018).
LGALS3BP also shares sentences with these, for which no sentence is quoted: fibrosis (11 papers); chronic hepatitis C (5); Chronic Hepatitis B (4); AIDS (3); cardiovascular disease (3); influenza (3); liver cirrhosis (3); non-alcoholic fatty liver disease (3); adenocarcinoma (2); autoimmune disease (2); metabolic syndrome (2); nasopharyngeal carcinoma (2); Oral Squamous Cell Carcinoma (2); periventricular nodular heterotopia (2); pleural mesothelioma (2); acute myeloid leukemia (1); age-related macular degeneration (1); alexithymia (1); Anxiety (1); Arthritis (1); Ascites (1); Ataxia (1); autism (1); autism spectrum disorder (1); autoimmune hepatitis (1); benign prostatic hyperplasia (1); bile duct cancer (1); brain tumor (1); bronchopulmonary dysplasia (1); carcinoid tumour (1).
A further 50 diseases each share a sentence with LGALS3BP in 1 paper.